RN7SL827P (RNA, 7SL, cytoplasmic 827, pseudogene)
Gene: Miscellaneous RNA gene on chromosome 6 (73,487,590 to 73,487,877, reverse strand). Ensembl gene ENSG00000271986.
Homologues: Orthologues: chimpanzee Metazoa_SRP (99% identical), macaque Metazoa_SRP (86% identical). Paralogues in human: RN7SL1 (87% identical), RN7SL2 (87% identical), RN7SL3 (85% identical), RN7SL507P (83% identical), RN7SL664P (83% identical), RN7SL712P (83% identical), RN7SL220P (82% identical), RN7SL113P (82% identical), RN7SL126P (82% identical), RN7SL296P (82% identical), RN7SL559P (82% identical), RN7SL709P (82% identical), and 703 more.